FGFR2 (fibroblast growth factor receptor 2)
Diseases named in the same sentence as FGFR2 in open-access papers (continued):
Sharing a sentence is not in itself a finding about the gene and the disease.
tumor (continued). "Patients with tumours displaying immunoreactivity for either or both FGFR2 and RSK-P had 4.89-fold higher risk of recurrence when compared to the FGFR2/RSK-P-negative subgroup." (PMID 27476168, 2016). "One tumor exhibited high-level amplification of a component with two low-level amplifications (high FGFR2/low KRAS and EGFR amplification in one case)." (PMID 27014419, 2016). "In primary tumour samples of BCa, we found a positive, statistically significant correlation between FGFR2 and RSK2 expression at both mRNA and protein levels." (PMID 27476168, 2016). "In 108 FGFR2-positive cases, the mean percentage of FGFR2-positivity was 57 ± 22% of the tumor (range, 5% to 100%), indicating heterogeneous FGFR2 expression in EGJ adenocarcinoma." (PMID 26933914, 2016). "Tumor shrinkage was also seen in a patient with adrenal carcinoma with FGFR3-TACC3/FGFR2- CCDC6 (FGFR3-TACC3 being the predominant translocation), who received treatment for 10 months before disease progression." (PMID 27409839, 2016). "Another study reported lower levels of FGFR2 mRNA and protein expression in tumour compared with normal breast tissue." (PMID 27236187, 2016). "Fibroblast growth factor receptor 2 (FGFR2) genetic alterations lead to tumor cell proliferation in various types of cancer." (PMID 26933914, 2016). "In tumor cells, the interaction between FGFR2, the progesterone receptor and STAT5 in the nucleus after FGF2 and medroxyprogesterone acetate (MPA) treatment has been associated with increased gene transcription and cell proliferation." (PMID 25970615, 2015). "Overexpression of FGFR2 was validated by qPCR, immunohistochemistry and western blot analysis in primary tumor samples." (PMID 26036639, 2015). "As PI3K and Akt are reported downstream signalings of FGFR2 and also involving in tumor growth, we detected the PI3K and Akt by western blot and RT-PCR." (PMID 26575424, 2015). "Taken together, our results indicate that formononetin targets the FGFR2-mediated Akt signaling pathway, leading to the suppression of tumor growth and angiogenesis." (PMID 26575424, 2015). "In qPCR analyses a clear up-regulation of FGFR2 gene expression was detected in cryo-conserved as well as in formalin-fixed tumor samples confirming the overexpression identified by microarray analyses in the whole tumor cohort." (PMID 26036639, 2015). "Proper patient selection based on FGFR2 status of the tumor will be critical when testing the inhibitor in future clinical trials." (PMID 26675289, 2015). "In another patient whose tumor possessed an FGFR2-TACC3 fusion, preliminary anti-tumor activity of pazopanib (in vitro FGFR2 IC50≈350 nM) was also noted." (PMID 24550739, 2014). "In the murine MMTV-PyMT tumor model Fgfr2 is overexpressed in the CD29HiCD24+ tumor initiating cell population and is necessary to initiate tumorigenesis in these mice." (PMID 25079073, 2014). "She had been treated with pazopanib 800 mg orally daily for 4 months and demonstrated tumor shrinkage, which in retrospect, was postulated to be secondary to the FGFR2 inhibitory activity of pazopanib." (PMID 24550739, 2014). "In one example, preliminary anti-tumor activity of pazopanib (in vitro FGFR2 IC50≈350 nM) was noted in a patient with an FGFR2-TACC3 fusion." (PMID 24550739, 2014). "While such a possibility would be surprising given recent reports that FGFR2 acts as a negative regulator of NFκB activity and suppresses tumor growth in UC cells, it is consistent with our finding that FGFR2 can also interact with TAK1." (PMID 24466111, 2014). "Two of these patients were able to receive targeted therapy for FGFR2 with resulting tumor shrinkage." (PMID 24550739, 2014).
tumor (continued). "A very recent RNA-Seq study detected 113 tumor-specific alternatively spliced genes among which a renal-specific switch between the epithelial FGFR2 IIIb isoform to mesenchymal FGFR2 IIIc isoform." (PMID 24194935, 2013). "In contrast, the majority of FGFR2-knockdown tumor cells gave rise to the terminally differentiated, myoepithelial lineage (SMA+ and K18−K14+)." (PMID 23300950, 2013). "It is possible that the inhibition of other TIC-specific genes along with FGFR2 inhibition produces synergistic anti-tumor activity, more effective at eradicating tumor initiating cells." (PMID 23300950, 2013). "To exclude the possibility that the observed growth inhibition was due to off-target effects of the shRNAs, we performed rescue experiments by ectopically expressing shRNA-resistant FGFR2 in tumor cells suppressed by shFGFR2." (PMID 23300950, 2013). "Flow cytometry analysis revealed ∼6-fold higher ALDH activity in the FGFR2+ population compared to the FGFR2- population, indicating that human breast TICs were enriched in the FGFR2+ population that was sufficient to initiate tumor growth." (PMID 23300950, 2013). "Two different shRNAs targeting different regions of FGFR2 displayed greater than 70% knockdown of the FGFR2 mRNA level and a strong reduction in the level of FGFR2 protein in tumor cells stably transduced with the lentiviral shFGFR2s." (PMID 23300950, 2013). "Given our expression profiles displaying the high expression of FGFR2 in breast TICs, we investigated the role of FGFR2 in tumor initiation through the self-renewal and maintenance of breast TICs." (PMID 23300950, 2013). "In conclusion, although KRAS and FGFR2 mutations share similar activation of the MAPK pathway, our data suggest very different roles in tumor biology." (PMID 22383975, 2012). "Decreased expression of FGFR2 in CRC cells was associated with inhibited cell migration, invasion, and tumor growth in vitro and in vivo." (PMID 22701813, 2012). "Tumor-derived fibroblasts expressed, on average, eight times more FGFR2 mRNA than the corresponding fibroblasts from normal breast tissue." (PMID 21767389, 2011). "Our cohort was probably underpowered to demonstrate a correlation between ER status of the tumor and FGFR2 mRNA expression levels in skin fibroblasts." (PMID 21767389, 2011). "Tumour sections were stained for FGFR2 protein expression, and scored for nuclear and cytoplasmic staining in tumour and surrounding normal tissue." (PMID 21418638, 2011). "FGFR2 immunohistochemistry demonstrated variable nuclear staining in normal tissue and tumour tissue, as well as consistent cytoplasmic staining." (PMID 21418638, 2011). "The factors that control this expression phenotype are therefore interesting in understanding how the control of FGFR2 expression relates to tumour formation and genotype." (PMID 21418638, 2011). "FGFR2 mRNA expression in tumor-derived fibroblasts was on average eight times higher than in breast fibroblasts and sixteen times higher than in skin fibroblasts (P = 3 × 10-4 and P = 2 × 10-4, respectively; paired t-tests)." (PMID 21767389, 2011). "This suggests that FGFR2 expression and localisation in tumour tends to reflect the expression and localisation in the background tissue it arises from." (PMID 21418638, 2011). "Since FGF10 is known to be secreted by fibroblasts and to bind specifically to the FGFR2-IIIb isoform expressed on epithelial cells, however, our findings would fit a model of paracrine tumor-stroma interaction." (PMID 21767389, 2011). "In our previous study, FGFR1 and FGFR2 expression was widely observed in both tumour cells and ECs of the human HNSCC xenograft model." (PMID 21063405, 2010). "Isoform-specific radiotracers could distinguish epithelial FGFR2-IIIb from mesenchymal FGFR2-IIIc isoforms, or identify truncated decoy receptors, thereby refining tumor classification, revealing spatial heterogeneity, and guiding therapeutic decisions." (PMID 41584352, 2026).
tumor (continued). "Furthermore, knockdown experiments using FGFR2 shRNA confirmed tumor dependency on FGFR2-IIIc, reinforcing its potential as a precision oncology target." (PMID 41584352, 2026). "Additionally, KIN-3248 has exhibited anti-tumor activity in FGFR2/3-driven advanced solid tumors, though its optimal clinical dose remains undetermined." (PMID 41584352, 2026). "This potential benefit arises because FGFR2 inhibitors inhibit tumour cell proliferation." (PMID 40861435, 2025). "iCCA cells secrete FGF1, which activates FGFR2 signaling to sustain tumor growth." (PMID 41430037, 2025). "Indeed, both infigratinib and erdafitinib were shown to be efficacious in UPS cell lines derived from a subset of patients carrying FGFR2 amplification, while erdafitinib also reduced in vivo growth of tumours formed by one of the FGFR2 amplified cell lines." (PMID 40415599, 2025). "Furthermore, the percentages of positive FGFR2 and FGFR3 tumor cells were negatively associated with the degrees of tumor differentiation." (PMID 41467942, 2025). "Molecular profiling of Western intrahepatic iCCA cohorts reveals IDH1 genomic alterations in 13% of cases and FGFR2 fusion events in 8%–14%.32, 33, 34 In this study, we detected an FGFR2 fusion in both tumor tissue and matched bile samples, while it was undetectable in plasma cfDNA." (PMID 41399682, 2025). "Longitudinal tumour biopsies collected during FGFR inhibitor trials will ultimately clarify which phospho signatures predict response and whether secondary mutations in FGFR2 or its downstream effectors emerge under therapeutic pressure." (PMID 41150770, 2025). "It is currently the only FGFR2-targeting drug with Breakthrough Designation by the FDA for frontline treatment of FGFR2b-overexpressing (defined as >10% of tumor cells staining positive for FGFR2b IHC) metastatic and locally advanced gastric and gastroesophageal adenocarcinoma." (PMID 41303727, 2025). "In luminal tumours, FGFR2 and ER pathways may thus act synergistically to regulate selective immune cell recruitment and establish a microenvironment permissive to immune evasion." (PMID 41018083, 2025). "Moreover, treatment with either an AKT3 inhibitor or an FGFR2 inhibitor significantly attenuates tumor progression in patient-derived xenograft models." (PMID 40057671, 2025). "Two patients with high-level FGFR2-amplified metastatic gastric cancer were successfully treated with futibatinib after progression on multiple lines of chemotherapy, with significant tumor shrinkage, symptom relief, and reduced tumor marker levels." (PMID 41303727, 2025). "On the other hand, there are indications that FGFR2 can act as a tumor suppressor in the skin." (PMID 40724880, 2025). "In contrast, G2 tumors showed a higher level of FGFR2 expression, which may reflect increased activation of signaling pathways involved in tumor proliferation and progression." (PMID 40806365, 2025). "Moreover, ICC exhibits unique mutation enrichments, such as IDH1/2 mutation, NTRK gene fusions, FGFR2 fusions/rearrangements, and RET fusions, particularly IDH1 mutations, which have higher mutation frequencies than other tumor types." (PMID 41236411, 2025). "Additionally, the MUC5AC and FGFR2 protein expression levels were positively correlated in the tumor tissues." (PMID 41467942, 2025). "Under physiological conditions, the FGF/FGFR2 signaling pathway plays important roles in embryonic development, tissue repair, tumor angiogenesis, and proliferation but FGFR2 fusions or rearrangements can lead to constitutive activation of the receptor, driving tumorigenesis and progression." (PMID 40585845, 2025). "Considering the individual differences of patients, such as the impact of PDL1 expression level, tumor mutation load, HRR mutation, expression of the FGFR2/3 genes and other factors on the therapeutic effect, more precise treatment plans can be formulated for patients with advanced or metastatic UC." (PMID 40821840, 2025).
tumor (continued). "Furthermore, the AKT3 and FGFR2 overexpression is significantly correlated with the late clinical stage, large tumor size, increased lymph node metastasis and poor prognosis." (PMID 40057671, 2025). "Prospective studies integrating transcriptomic and spatial profiling approaches will be instrumental in clarifying this crosstalk and may inform rational therapeutic strategies targeting both tumour-intrinsic FGFR2 signalling and the TIME." (PMID 41018083, 2025). "Moreover, FGFR2 expression was significantly associated with tumor stemness and EMT markers, including CD133, CD44, VIM, and N-cadherin, underscoring the role of the SFRP1-FGFR2 interaction in CRLM." (PMID 40225580, 2025). "In this context, FGFR2 may play an active, subtype-specific role in shaping the immune landscape during tumour evolution, contributing to the transition from DCIS to IDC even in tumours with initially low baseline immune activity." (PMID 41018083, 2025). "The single tumor that lacked FGFR2 mutations harbored a CTNNB1 p.I35T variant and showed more favorable histologic features." (PMID 40906279, 2025). "Moreover, the differential correlations observed only in luminal A tumours—despite similar levels of FGFR2 expression across subtypes—highlight the importance of hormonal context in modulating FGFR2-immune interactions." (PMID 41018083, 2025). "While co-mutations of FGFR2 with PIK3CA or truncating exon 18 FGFR2 variants occur in other tumor types, these have not previously been reported in sialoblastoma." (PMID 40906279, 2025). "The findings indicate that FGFR2 was involved in tumor development and progression." (PMID 40806365, 2025). "Next-generation sequencing (NGS) of tumor-normal DNA and tumor RNA under Lenvatinib treatment confirmed the FGFR2 fusion, however no further molecular resistance mutation was observed." (PMID 40260297, 2025). "Furthermore, higher levels of FGFR2 and FGFR3 expression were associated with worse survival of PDAC patients and negatively correlated with tumor differentiation." (PMID 41467942, 2025). "Furthermore, KIN-3248 exhibited dose-dependent tumor inhibition in FGFR2/3-driven cholangiocarcinoma, gastric, and bladder cancer xenograft models." (PMID 38602417, 2024). "FGFR2 fusion frequency in iCCA is approximately 10–15% across multiple tumor genotyping studies." (PMID 38255923, 2024). "Interestingly, among the 21 FGFR2-positive cases, we identified two distinct subgroups of patients on the basis of FGFR2 signalling activation in the tumor tissue." (PMID 38326380, 2024). "A correlation analysis showed that FGFR2 status did not correlate with tumor-associated macrophages (TAMs; P > .05)." (PMID 38986528, 2024). "mAbs can also be conjugated to cytotoxic agents, as seen in BAY 1187982, a combination of BAY 1179470 and auristatin, which demonstrated potent anti-tumor activity in FGFR2-positive advanced cancers by specifically delivering toxicity to FGFR2-expressing cells." (PMID 39796710, 2024). "Furthermore, the interaction between HPV16 E5 and FGFR2 alters keratinocyte differentiation and inhibits tumor-suppressive genes, suggesting a role in the early stages of HPV infection and transformation." (PMID 39024554, 2024). "In addition, one tumor contained a high-copy FGFR2 gene amplification accompanied by strong overexpression of the gene." (PMID 39596194, 2024). "EGFR and FGFR2 play an essential role in tumor angiogenesis and, therefore, may increase the probability of hemorrhage, which may, in turn, lead to a poorer prognosis." (PMID 38877400, 2024). "Despite their potential anti-tumor activity, they are ineffective at overcoming commonly acquired FGFR gatekeeper mutations (FGFR1 V561M, FGFR2 V564F, FGFR3 V555M, FGFR4 V550M/L) and other mutations including an FGFR1 N546K mutation and FGFR2 N550H mutations." (PMID 38255923, 2024).
tumor (continued). "An important issue that remains to be clarified, however, is whether chemotherapy may lead to a selection of tumor cell subclones with FGFR2 GAs, a molecular event that may confer resistance to the chemotherapy itself." (PMID 38326380, 2024). "Disruptions in FGFR2 signaling contribute to tumor development and cancer progression." (PMID 39195304, 2024). "Therefore, FGFR2-positive cHCC-CCAs and nestin-positive cHCC-CCAs share similar features such as smaller tumor size, the more frequent presence of CLC components, and multiple genetic alterations." (PMID 38532197, 2024). "Furthermore, FGFR2-amplified GCs are more likely to be of high tumour grade, and of diffuse-type histology, and several studies have associated FGFR2 amplification status with poorer survival outcomes." (PMID 38791079, 2024). "A low FGFR2 may be better for tumour progression because ligands that would otherwise bind to FGFR2 in the ECM now bind to other receptors, initiating different pathways." (PMID 39596875, 2024). "The collaborative signaling among EGFR, PDGFRα, PDGFRβ, and FGFR2 proteins could result in a synergistic effect on promoting tumor progression making them valuable targets for cancer therapy." (PMID 38338684, 2024). "FGFR2 IIIc overexpression correlates with tumour growth and metastasis." (PMID 39596875, 2024). "We present a case of high-grade serous carcinoma of Mullerian primary with a novel FGFR2::IQCG fusion an exceedingly rare combination of tumor type and fusion class, which progressed through multiple lines of therapy before and after a brief period on futibatinib." (PMID 39759134, 2024). "Other immunohistochemistry-based studies that have examined the overall frequency of FGFR2 expression or overexpression in GC relative to normal gastric mucosa, have reported expression ranges between ~30% to as high as 61% of tumours." (PMID 38791079, 2024). "Similarly, using IHC, the FGFR2 expression levels in HER2-positive tumours were significantly lower than in ER+ or TNBC tumours." (PMID 39596875, 2024). "FGFR2 fusion/rearrangement was associated with low levels of carcinoembryonic antigen (CEA, P = .026) and gamma glutamyl transferase (γ-GGT, P = .003), low TNM (P = .012), CNLC (P = .008) staging as well as low tumor cell differentiation (P = .016)." (PMID 38986528, 2024). "In addition, other families of amplification events, such as FGFR2 amplification and activation of other FGFR mutations, have been associated with the maintenance of tumour-initiating cells as well as high sensitivity to FGFR inhibitors." (PMID 40135140, 2024). "Specifically, tumor-associated fibroblasts (TAFs), a type of stromal cell in the TME, have been implicated in promoting trastuzumab resistance via fibroblast growth factor receptor 2 (FGFR2) activation in HER2+ BC cells." (PMID 39123362, 2024). "One possible strategy for more successfully predicting the response to FGFR2 inhibitors could be the use of circulating tumour DNA (ctDNA) technology." (PMID 38791079, 2024). "We then created a new fusion trimer peptide ACSAG-LPHVLTPEAGAT-GASCA (Trimer-pep) and investigated its binding interactions with the FGFR2 kinase domain in order to target the fibroblast growth factor receptor 2 (FGFR2), which is many overexpressed in tumor cells." (PMID 39329537, 2024). "Our investigation revealed that the tumor-driver potential of gain-of-function mutant FGFR2 depends on ADAM17-mediated MAPK activation, while the overexpression of loss-of-function FGFR2 mutants showed only minimal tumorigenicity in the absence of other driver alterations in cell-based assays." (PMID 37759450, 2023). "The staining of pAKT overlapped with FGFR2 detection at the EOCC tumor invasive margin." (PMID 37964075, 2023). "Significant anti-tumor efficacy was observed in 2 models: BCX.066, which had FGFR2 amplification/overexpression; and PDX.007, which had FGFR2 Y375C mutation and FGFR2 amplification." (PMID 37980453, 2023).